CD163 (CD163 molecule)
Diseases named in the same sentence as CD163 in open-access papers (continued):
Sharing a sentence is not in itself a finding about the gene and the disease.
viral infection (52 papers, 2010 to 2026). "In our analysis, CD163 expression in immunological organs was associated with tissue-specific variations in virus infection." (PMID 39568484, 2024). "Consistently, other study also showed that challenge of CD163 SRCR5-edited pigs with highly pathogenic PRRSV (HP-PRRSV) confers resistance to virus infection and the biological functions of CD163 are intact." (PMID 36187992, 2022). "BHK-21 cells are refractory to PRRSV infection, while they are susceptible to viral infection with CD163 expression." (PMID 35138165, 2022). "The elevated level of CD163 with the subsequent shedding is an emerging marker of virus infection associated macrophage activation syndrome with dismal outcome." (PMID 34056141, 2021). "Calpain 1 is identified as a novel protein associated with viral infection that interacts with CD163 to facilitate PRRSV uncoating in the EE." (PMID 32038556, 2019). "Pro-inflammatory and anti-inflammatory effects caused by virus infection were demonstrated to associate with CD163 expressed on immune cells." (PMID 29121904, 2017). "Deletion of the SRCR5 domain of CD163 prevents viral infection while largely preserving normal receptor function, representing a more targeted approach compared with complete gene knockout." (PMID 42286732, 2026). "Current research indicates that blocking the binding of CD163 to PRRSV can effectively prevent viral infection." (PMID 40823990, 2025). "Further research has demonstrated that the SRCR5 domain is essential for viral infection, while pigs with a CD163 SRCR5 gene defect are resistant to NA-type PRRSV strains." (PMID 40005815, 2025). "Removal of N-glycosylation sites did not affect the capacity of CD163 to allow both PRRSV-1 and PRRSV-2 infections, since viral infection was detected in cells expressing the mutant CD163." (PMID 38776134, 2024). "Exogenous ligands of CD163 are bacteria and viruses, which activate the macrophages during bacterial and viral infections, respectively." (PMID 39451197, 2024). "We observed a significant increase in the expression of Sn, CD163, and vimentin following viral infection." (PMID 39568484, 2024). "In previous studies, on drug treatment before viral infection, natural plant compounds reduced the adsorption and invasion of PRRSV-susceptible cells by altering the expression of receptors, such as CD163 and CD151." (PMID 39228381, 2024). "This should be particularly taken into account in experiments dealing with porcine reproductive and respiratory syndrome virus (PRRSV), because CD163 is an essential receptor for virus infection." (PMID 36290361, 2022). "Non-muscle myosin heavy chain 9 (MYH9), identified as a cell receptor for PRRSV, interacts with CD163 to promote virus infection." (PMID 36187992, 2022). "Pretreatment of MARC-145 cells with an anti-CD163 antibody nearly blocked C1 virus infection, indicating that the virus still required CD163 to infect cells." (PMID 36560826, 2022). "CD163 fifth SR cysteine-rich domain (SRCR5) is further proven to play a crucial role during viral infection." (PMID 34193250, 2021). "Previous studies have shown that PRRSV infects host cells via low pH-dependent CME (21, –, 23) and a scavenger receptor CD163 is indispensable for viral infection (24, –, 27)." (PMID 32522856, 2020). "Taken together, these data demonstrate that TREM2 knockdown decreases cytokine-mediated CD163 expression to inhibit virus infection via Syk/PI3K and TLR4/NF-κB signaling." (PMID 32401783, 2020). "And finally, CD163-knockout pigs were completely resistant to viral infection during the PRRSV challenge due to the fact that this gene acts as a cellular receptor for PRRSV27." (PMID 32350307, 2020). "The PS receptor TIM-1/4 recognized PRRSV and induced the downstream signaling pathway to mediate viral infection via CD163-dependent macropinocytosis." (PMID 32522856, 2020).
viral infection (continued). "Previous studies have revealed that CD163 mediates PRRSV uncoating instead of internalization for productive viral infection." (PMID 32727587, 2020). "Infection by PRRSV is previously shown to be via low pH-dependent clathrin-mediated endocytosis, and CD163 functions as an essential receptor during viral infection." (PMID 32522856, 2020). "CD163 has been defined as the main receptor for viral infection by evaluating the effect of PRRSV on CD163 knockout pigs, where there is complete resistance to infection." (PMID 30842948, 2019). "The results showed the PAMs from the modified CD163 were completely protected from the viral infection in vitro, but the pigs showed a transient viremia after the infection, and one pig died in the viral challenge." (PMID 31523199, 2019). "Although deletion of CD163, a fusion receptor for PRRSV, has been described resulting in a significant resistance to the virus infection, the CD163−/− pigs still have a risk of infection with other pathogens that do not depend on this receptor." (PMID 29326720, 2017). "A possible explanation for these findings is that binding of ASFV to CD163 is necessary for some virus infection." (PMID 24398227, 2014). "For Marc-145 grown virus infection of CHOSn-CD163 cells, little difference was observed between different cell densities and days post seeding, although a density of 200 000 cells/mL and inoculation at 2 days post seeding seemed a little more efficient." (PMID 20587060, 2010). "At 3 and 5 dpi, the highest amount of virus infection was achieved, with up to 20% for Marc-145 grown LV and up to 40% for Marc-145 grown VR-2332 on CHOSn-CD163 cells and up to 80% for both Marc-145 grown strains on PK15Sn-CD163 cells." (PMID 20587060, 2010). "To test this possibility, we analysed the impact of CD163 N-glycosylation on viral infection." (PMID 38776134, 2024). "Instead, it is likely that viral infection leads to the downregulation of CD163 expression." (PMID 39723134, 2024). "To determine if viral infection status impacts the local population of susceptible cells, we evaluated the gene expression of CD163 across six non-lymphoid fetal tissues from PRRSV infected gilts." (PMID 38389522, 2024). "Similarly, 12-O-tetradecanoylphorbol-13-acetate (TPA) treatment leads to reduced expression of CD163 thus hindering virus infection." (PMID 36187992, 2022). "All three lncRNA-mRNA pairs, including lncRNA XLOC-022175 vs CXCL2 (co-upregulated), XLOC-019295 vs IFI6 (co-upregulated), and XLOC-017089 vs CD163 (co-downregulated) exhibited significant changes after virus infection, which coincided with the predicted correlation networks." (PMID 33711920, 2021). "Moreover, the significant increase in MFI of CD163+ in PRRSV-infected pigs probably was due to the polarization of the M2 phenotype after infection, and indicates that CD163 plays an important role in receptor for viral infection." (PMID 34579246, 2021). "To understand the role of CD163 N-glycosylation in viral infection, we generated an N-glycosylation-deficient mutant fused to FLAG, in which all the N present in the consensus N-glycosylation sites were replaced by Q (for clarity, this new mutant is herein referred to as CD163-FLAG*)." (PMID 38776134, 2024). "To demonstrate that TREM2 knockdown reduces cytokine-mediated CD163 expression to inhibit virus infection via Syk/PI3K and TLR4/NF-κB signaling, we first explored whether TREM2 knockdown promotes the expression of proinflammatory cytokines and type I interferons via these pathways." (PMID 32401783, 2020). "In some viral infections, such as HIV infections, serum sCD163 levels and CD163 expression levels on monocyte populations are recently known to be associated with clinical status and antiretroviral therapy." (PMID 29445750, 2017). "The CD163, ANPEP, DNAJC14, and ANTXR1 knockout pigs proved resistant to viral infections." (PMID 41465565, 2025).
viral infection (continued). "It has been shown that disruption of the Scavenger Receptor Cysteine-Rich Domain 5 (SRCR5) of porcine CD163 gene located on exon 7 guarantees complete resistance to viral infection without any adverse effects in pigs." (PMID 41465565, 2025). "Finally, we evaluated the impact of viral infection on the local immune response by quantifying IFNG and CD163 expression." (PMID 38389522, 2024). "This indicated that CD163 alone is not sufficient for virus infection, in accordance with studies previously reported in this review (see Section 2.1)." (PMID 35632463, 2022). "Arg561 in the CD163 long ring region is an important residue for PRRSV invasion, and may play a key role in the interaction of CD163 and PRRSV during viral infection, providing a target for drug design and gene editing." (PMID 35681845, 2022). "It is difficult for only one receptor to mediate the whole process of the virus infection, although CD163 has been reported to be sufficient to convert the non-permissive cell lines to fully permissive cell lines for PRRSV infection." (PMID 35694306, 2022). "Blocking viral infection in the binding or attachment step and binding of PRRSV to the receptor on the SRCR5 position of the CD163 protein may help to decrease the PRRSV pandemic." (PMID 36517668, 2022). "Together, the results indicate that CD163 is necessary but not sufficient for the C1 virus infection." (PMID 36560826, 2022). "Furthermore, we investigated the correlation between viral infection status (EBER1 and HPV16/18), MIF, and macrophage markers (CD68, CD11c, and CD163) in NPC cases using Spearman’s correlation test." (PMID 34407796, 2021). "Therefore, the specific antibody directed against the CD163 SRCR5 domain generated in this study provides a tool for functional studies of CD163 and further investigation into the link between CD163 and viral infection." (PMID 33251273, 2020). "Since CD163 is necessary for viral infection and replication, the logical next step is to identify the conserved regions of viral surface proteins, most likely the minor glycoproteins (GP2, GP3, and GP4), that interact with CD163." (PMID 28608816, 2017). "CHOSn-CD163 clones IC5, ID9 and IF3 were equally sensitive to virus infection." (PMID 20587060, 2010). "The CD163 cytoplasmic tail is also not obligatory for PRRSV infection, and whether CD163 is expressed on the cell surface is not related to productive viral infection, but its transmembrane region is indispensable for viral replication." (PMID 39651859, 2025). "In addition, here, we show that removal of the N-glycosylation sites, by mutagenesis of CD163 did not disrupt its ability to support viral infection in non-permissive transfected cells." (PMID 38776134, 2024). "Taken together, these data suggest that CD163 SRCR5-edited pigs are resistant to PRRSV 2, providing a basis for the establishment of PRRSV-resistant pig lines for commercial application and further investigation of the essential region of SRCR5 involved in virus infection." (PMID 31440241, 2019). "However, Siglec-3 and Siglec-5did not seem to play a role in infection, which further confirmed our resultsshowing that the non-permissive cell line expressing Siglec-3 or Siglec-5 incombination with CD163 did not improve virus infection and production." (PMID 28742001, 2017). "Taken together, our results here are consistent with the mechanism discovered previously that CD163 interacts with PRRSV GP2a and GP4 to mediate PRRSV uncoating after endosome acidification to ensure effective viral infection, rather than mediating the viral binding and internalization." (PMID 32727587, 2020).
diabetes (49 papers, 2012 to 2025). "Deep RNA profiling of circulating CD163+ monocytes in our study revealed that in those with diabetes-related complications, the genes associated with the ‘regulation of centrosome cycle’ were up-regulated and enriched." (PMID 39337580, 2024). "Soluble CD163 is a biomarker of macrophage activation that is associated with the development of diabetes." (PMID 33716989, 2021). "Our findings are in line with a large prospective cohort study, which found a significantly increased risk of incident diabetes in subjects with high baseline CD163 levels." (PMID 30670722, 2019). "Our study confirmed previously established associations with incident diabetes for CD163, FABP4, PAI, and IGFBP-2." (PMID 30670722, 2019). "Further studies are needed to elucidate the mechanisms underlying the relationship between monocyte CD163 and insulin resistance in obese and diabetes." (PMID 29445750, 2017). "When further adjusting for established risk factors (model 2), all 7 proteins remained significantly associated with incident diabetes; 5 proteins (CD163, Gal-4, CTSD, PAI and FABP4) with an increased risk of diabetes and 2 proteins (PON3 and IGFBP-2) with a decreased risk for incident diabetes:." (PMID 30670722, 2019). "CD163 expression tends to be low in conditions such as non-alcoholic fatty liver and ischemic cardiomyopathy, whereas sCD163 tends to be elevated in hypertension and diabetes." (PMID 40630963, 2025). "CD163, a scavenger receptor with anti-inflammatory function expressed exclusively on monocytes/macrophages, is dysregulated in cases of diabetes complications." (PMID 39337580, 2024). "Enriched centrosome cycle genes and up-regulated miRNAs linked to apoptosis, coupled with down-regulated monocyte activation, recruitment, and immune regulation, suggest functionally distinct CD163+ monocytes in cases of diabetes complications." (PMID 39337580, 2024). "While we have comprehensively profiled the RNA transcriptome and surface marker phenotype of CD163+ monocytes in the context of diabetes complications, further research is needed to uncover the causative mechanisms underlying this distinct cell profile." (PMID 39337580, 2024). "The anti-inflammatory myeloid scavenger receptor CD163 has been reported to be decreased in people with diabetes complications." (PMID 39337580, 2024). "In conclusion, this study reports novel insights into CD163+ monocyte dysregulation in diabetes-related complications." (PMID 39337580, 2024). "This study aimed to characterize circulating CD163+ monocytes in the presence (D+Comps) or absence (D−Comps) of diabetes-related complications." (PMID 39337580, 2024). "We observed an increased expression of the gene CD5 in CD163+ monocytes in individuals with diabetes-related complications." (PMID 39337580, 2024). "Our results suggest that CD163+ monocyte-mediated T cell activation was down-regulated in individuals with diabetes-related complications, due to the increased CD5 and decreased CD86 expression." (PMID 39337580, 2024). "In renal complications, CD163+ cells in the glomeruli were reported to be positively correlated with the progression of nephropathy in individuals with diabetes." (PMID 39337580, 2024). "Our finding of potentially increased cellular apoptosis of circulating CD163+ monocytes would explain the previous finding of decreased circulating peripheral CD163+ monocytes in individuals with diabetes-related complications." (PMID 39337580, 2024). "While CD163+ monocytes/macrophages have been studied across various diabetes complications, how CD163+ monocytes are dysregulated in diabetes complications is unclear." (PMID 39337580, 2024). "This anti-inflammatory capacity is decreased in diabetes mellitus, as CD163 mRNA expression in peripheral blood mononuclear cells (PBMCs) is significantly suppressed in newly diagnosed diabetic patients." (PMID 35163309, 2022).
diabetes (continued). "So far, a number of studies have tried to elucidate the role and regulation of CD163 in pathological conditions, such as diabetes mellitus or inflammation, altogether." (PMID 35163309, 2022). "Significantly more work is required to understand the role of the TWEAK/Fn14/CD163 axis alongside other inflammatory cytokines in the context of diabetes." (PMID 34542797, 2022). "Soluble CD163 has previously been associated with HOMA‐IR, a surrogate measure of hepatic IR, in patients with diabetes as well as obese and normal‐weight subjects." (PMID 35040267, 2022). "It has been reported that monocyte CD163 expression is reduced in diabetes and CD163 is strongly induced by IL-10 in macrophages." (PMID 32879134, 2020). "In the future, the CD163 protein can aid as a signaling molecule in the earlier detection of periodontal disease and diabetes mellitus." (PMID 32656036, 2020). "Diabetes is known to downregulate CD163, the hemoglobin:haptoglobin (Hb:haptoglobin) scavenger receptor." (PMID 32879134, 2020). "The fluorescence intensity increased with increasing drug loading, with tissues samples from animals treated with DPFI-3 showing fluorescence intensities for CD163 and HO-1 that were 25.7 and 28.7 times higher than those observed in the diabetes group, respectively." (PMID 40757164, 2025). "This suggests that the unresolving nature of diabetes-related complications may be due to the dysregulated interaction between the antigen-presenting CD163+ monocytes and the adaptive immune system." (PMID 39337580, 2024). "Furthermore, in diabetes-related complications, CD163+ monocyte-mediated immunosuppression was potentially reduced due to the decreased expression of the immune inhibitory receptor CD200R1." (PMID 39337580, 2024). "In conclusion, this study is the first to comprehensively characterize the RNA profile and phenotype of CD163+ monocytes in individuals with long-term diabetes and complications, presenting new implications for the role of CD163+ monocytes in diabetes-related complications." (PMID 39337580, 2024). "Additionally, in individuals with diabetes-related complications, CD163+ monocytes exhibit reduced abilities for cell recruitment and trans-endothelial migration, along with dysregulated activation of their adaptive immune system." (PMID 39337580, 2024). "The ability of the CD163+ monocytes to clear and regulate extracellular ATP may be potentially diminished in individuals with diabetes complications due to the decreased expression of the ectonucleotides CD39 and CD73." (PMID 39337580, 2024). "The elevated protein levels of CD163 in the subgingival plaque samples of generalized chronic periodontitis individuals with type II diabetes mellitus signify the involvement of CD163 in the pathogenesis of both periodontitis and diabetes mellitus." (PMID 32656036, 2020). "Within the limitation of this study, CD163 protein quantification has the insight to assess the progression of periodontitis and its impact on metabolic diseases, such as diabetes mellitus, thereby making them potent biomarkers for both these inflammatory conditions." (PMID 32656036, 2020). "There are few reports examining monocyte CD163 expression levels in diabetes." (PMID 29445750, 2017). "When further entering fasting plasma glucose (highly associated with incident diabetes; HR 1.30, 95% CI: 1.25–1.35; p = 9.1 × 10−39) as a covariate (model 3), the following four proteins remained significantly associated with increased risk of diabetes; PAI, Gal-4, CD163 and FABP4." (PMID 30670722, 2019). "Specifically, genes such as CCL17, CD163, APOE, CYP27A1, and STAB1, some of which are recognized as anti-atherogenic and anti-inflammatory factors in diabetes patients, were identified within this module." (PMID 38658734, 2024). "The three-way ANOVA showed that diabetes mellitus (p<0.0001) and CD64 KO (p<0.0001) significantly influenced the CD163+ macrophages." (PMID 38524127, 2024).